NRAS (NRAS proto-oncogene, GTPase)
Diseases named in the same sentence as NRAS in open-access papers (continued):
Sharing a sentence is not in itself a finding about the gene and the disease.
melanoma (continued). "The first trial is currently enrolling both NRAS mutant cutaneous melanomas and KRAS or BRAF mutant non-small cell lung cancers progressed after standard of care therapy, while the second one is focused on pre-treated BRAF or NRAS mutant melanomas." (PMID 34071228, 2021). "This view is consistent with our own findings that human NRAS-mutant melanoma cell lines and patient biopsies frequently but not generally show increased ERK5 activity." (PMID 34299213, 2021). "Gene expressions in mucosal melanomas like c‐KIT, NRAS or BRAF might be of potential use for selective inhibitors." (PMID 33844113, 2021). "Considering the lack of success of therapies targeting BRAF and MEK in NRAS mutant melanoma patients, recent efforts have been focused on finding other therapeutic targets and the development of combination therapies." (PMID 33921974, 2021). "Similarly, the expression levels of these genes were comparable in BRAF-, NRAS-, and NF1-mutant, as well as triple wild-type melanoma tumors indicating that the presence of mRNAs in qCLASH hybrids is not influenced by stage of disease or mutational background." (PMID 33806450, 2021). "In a phase 1 study using trametinib in advanced melanomas, trametinib did not demonstrate efficacy in the majority of patients with BRAF/NRAS wild-types, but one patient with an NF1 mutation had a stable disease." (PMID 34831002, 2021). "Only a subset of patients benefits from MEK inhibitors used as single agents, and they only produce cytostatic effects, rather than cytotoxic effects, in NRAS-mutant melanoma cells." (PMID 33921974, 2021). "In a word, compared with gynecologic melanoma, non-gynecologic melanoma harbored distinct mutation rates in KIT, BRAF, SF3B1, KRAS and NRAS genes." (PMID 34102999, 2021). "Nevertheless, a non-randomized multicenter phase 2 study using trametinib in combination with GSK2141795 (a pan AKT inhibitor) did not yield significant clinical activity in NRAS mutant melanomas." (PMID 34831002, 2021). "Intriguingly, in vitro inhibition of such “chromatin readers” is associated with cell cycle arrest in preclinical melanoma models, regardless of BRAF or NRAS mutational status." (PMID 34440824, 2021). "In NRAS-mutant melanoma patients, Binimetinib treatment also did not provide any measurable benefit as monotherapy (NCT01763164)." (PMID 34946644, 2021). "The use of MAPK inhibitors to radio-sensitize tumors to TRT appears to be a promising strategy in BRAF- and NRAS-mutant melanoma, although the lack of an in vivo study to confirm the results is the main limitation of this work." (PMID 33804655, 2021). "Previous study has reported that mutations and deletions of PTEN, negative AKT activation regulator, are more frequent in BRAF mutant rather than NRAS mutant melanomas." (PMID 33734579, 2021). "Such a model is not supported by the higher rate of NRAS-mutant melanomas in CSD skin but still requires further investigation." (PMID 34210801, 2021). "In all melanomas, real-time PCR did not disclose any BRAF mutation; melanoma #1 was KRAS and NRAS (lesions #2, 3, 4) wild type." (PMID 33614203, 2021). "BRAF fusions in mucosal melanomas have also been described, with a comparable frequency as of cutaneous triple wild type melanoma (i.e., lacking BRAF, NRAS, and NF1 mutations)." (PMID 35008570, 2021). "In line with previous studies of extracranial melanomas, none of our 16 sample pairs presented coexistence of BRAF and NRAS mutations." (PMID 33578810, 2021). "In melanoma, key oncogenic drivers, such as BRAF and NRAS, have been well defined." (PMID 34140478, 2021). "In a large series of 706 mucosal melanomas, KIT and BRAF mutational status did not correlate with overall survival (OS); however, NRAS was not analyzed in this series." (PMID 34571863, 2021). "Though NF1 mutations often occur in melanomas without BRAF or NRAS mutations, approximately 4% of the BRAF and NRAS mutated melanomas also harbor NF1 mutations." (PMID 35008286, 2021).
melanoma (continued). "Of the 28 melanoma cell lines, 22 harbored BRAF V600 mutations, 4 harbored oncogenic NRAS mutations, one was NF1‐mutant (in the absence of BRAF or NRAS mutations), and the remainingline was triple‐wild‐type." (PMID 32767816, 2021). "Taken together, our findings suggest RP11-705C15.3 as a novel oncogene in melanoma, and highlight that the RP11-705C15.3/miR-145-5p/NRAS/MAPK signaling axis may be potential therapeutic targets for melanoma." (PMID 33311650, 2021). "We initially examined TNFα signaling in response to exogenous TNFα in 40 melanoma cell lines, including 31 cutaneous (11 BRAF-mutant, 10 NRAS-mutant, 10 BRAF/RAS WT) and nine uveal melanoma cell lines (five GNAQ-mutant, three GNA11-mutant and one GNAQ/GNA11 WT)." (PMID 34073253, 2021). "Therefore, we generated tumor xenografts in mice using BRAF mutant A375 and WM47, NRAS mutant WM3000, and triple-wildtype WM3311 human melanoma cells." (PMID 33498757, 2021). "Combining BET (bromodomain and extra-terminal domain) family and MEK inhibitors synergistically inhibited the growth of NRAS-mutant melanoma in mice not responding to MAPK inhibitors." (PMID 34063141, 2021). "In addition, FUT8-AS1 functions as a tumor suppressor and inhibits proliferation, migration, and invasion of melanoma cells via binding to NF90, resulting in down-regulation of NRAS." (PMID 35096622, 2021). "PGC1α expression levels have been associated with the metabolic state of melanomas and the response to MEK inhibition independent of BRAF or NRAS mutation status." (PMID 33498757, 2021). "New approaches are needed to improve the outcomes of NRAS mutant melanoma, especially in noncutaneous melanoma." (PMID 34290710, 2021). "We have recently reported corroborating results on a xenograft model using NRAS-mutant melanoma cells: the co-inhibition of the MAPK/ERK pathway with trametinib and the MEK5/ERK5 cascade using the ERK5i XMD8-92 was effective in preventing melanoma expansion." (PMID 34299213, 2021). "Given the current lack of approved targeted therapies for NRAS mutant melanoma patients, MEK inhibitors offer a potential treatment option." (PMID 33921974, 2021). "In a study investigating the prognostic and predictive values of oncogenic BRAF, NRAS, c-KIT, and MITF in melanoma, it was found that initial lymph node involvement was more frequent in patients with BRAF-mutated melanomas, than in cases presenting other mutations." (PMID 34209415, 2021). "These are compelling results for NRAS-mutant melanoma patients since there are no targeted therapies currently approved." (PMID 33456709, 2021). "The oncogenic activities of mGluR1 expressing melanoma cells are independent of BRAF and NRAS mutations; additionally it has been found that a polymorphism in the GRM1 gene is predominately found in non-CSID melanoma patients." (PMID 34359771, 2021). "We performed transcriptomic analysis of three different melanoma lines, two with BRAF and one with NRAS mutations, with or without AR silencing with two different lentiviruses." (PMID 33112375, 2021). "RAC1 was previously pointed out as a key downstream effector of NRAS Q61K for tumor growth in melanoma, but no study has been conducted in thyroid cancer." (PMID 34831012, 2021). "Although the contribution of mutant NRAS and BRAF to MM progression appears to be less common than melanoma of the skin, more components in the MAPK pathway of MM tend to undergo mutations or copy number changes, rendering inhibition of MAPK signaling transduction more challenging." (PMID 34350118, 2021). "To determine whether FBXO42 KO indeed leads to resistance in NRAS‐mutant melanoma cells, we knocked out FBXO42 from NRAS mutant cell lines." (PMID 31549767, 2020). "While the contribution of somatic BRAF/NRAS mutations to melanoma is very important, our study did not reveal any evidence of germinal BRAF/NRAS mutations." (PMID 33748184, 2020).
melanoma (continued). "Underlying the clinical aspect of these studies, the co-targeting of BET and MEK has been proposed in NRAS mutant melanoma cell lines or for melanomas with no other therapeutic options to offset resistance to targeted and/or immunotherapies." (PMID 32042336, 2020). "Analysis of the TCGA cutaneous melanoma dataset also showed that methylation of the p16INK4a probe cg12840719 was higher in NRAS-mutant melanoma, compared to BRAF-mutant melanoma, although this was not statistically significant." (PMID 33076392, 2020). "Overall, cell line-specific expression patterns of miRNAs were apparent, reflecting the high intrinsic heterogeneity of melanoma cells, which were not influenced by presence of either the BRAF or NRAS mutations." (PMID 32183388, 2020). "Even though COX-2 expression did not correlate with BRAF/NRAS mutation status, it seems that BRAF-mutated melanomas have an increased COX-2 and PD-L1 expression via IL-1 upregulation." (PMID 32296574, 2020). "Importantly, TM also suppressed S6 phosphorylation in non-BRAF mutated melanoma cell lines indicating a broader therapeutic potential of TM in patients without the BRAF mutation but where the PI3K/Akt/mTOR pathway is activated such as in patients harboring NRAS mutations." (PMID 32085796, 2020). "PREX2 truncation E824∗ was found to cooperate with NRAS mutations but not with BRAF V600E mutation, to accelerate melanoma development." (PMID 32850962, 2020). "An important protein of the Ras‐signalling pathway identified within these clusters was the receptor tyrosine kinase IGF1R, for which several drugs already exist, but are not used in the context of NRAS‐mutant melanoma to the best of our knowledge." (PMID 33073517, 2020). "These combinations kill melanoma cells, regardless of their mutation status in BRAF or NRAS, likely because MCL1 and BCLXL are downstream of these common mutations." (PMID 32513939, 2020). "Importantly, the same concept proved successful in mutant NRAS-driven malignant melanoma, where BRD4 and MEK inhibitors synergized to inhibit tumor growth in mouse melanoma models." (PMID 32046099, 2020). "Beads, emulsion, amplification and magnetics (BEAMing) and droplet digital PCR (ddPCR), two PCR-based techniques, have very high sensitivity, but they are limited by the need for a specific gene target and hence used mostly in wild type melanoma for BRAF, NRAS or c-KIT." (PMID 33233603, 2020). "Globally, about two-thirds (184 cases) of Sardinian melanoma patients were found to carry a BRAF or NRAS mutation, even considering that some cases were not analyzed for NRAS mutations." (PMID 32751423, 2020). "A closer look revealed that the essentiality of IGF1R was significantly higher in NRAS‐mutant cell lines compared with NRAS‐WT background and also generally in BRAF WT melanoma cell lines, which is mainly composed of NRAS and HRAS mutants, compared with the BRAF V600E mutants." (PMID 33073517, 2020). "Giant congenital naevi are pigmented childhood lesions that often have NRAS mutations rather than BRAF mutations; the presence of these lesions also confers an enhanced risk of early onset melanoma." (PMID 33024276, 2020). "Acetate dependence is specific to BRAF mutant but not NRAS mutant or wild-type BRAF/NRAS melanoma cells." (PMID 33121001, 2020). "Because melanoma patients commonly harbor genetic alterations in BRAF, NRAS, CDKN2A, or NF1 genes that contribute to tumor progression, we examined potential associations between these genetic alterations and IRAK-M levels in melanoma cell lines and patient samples." (PMID 32533049, 2020). "Alterations of the CDK4/6 signaling pathway is observed in different types of melanoma, concomitantly with NRAS, KRAS or BRAF; thus the genetic profiling of CDK4/6 may provide insights for the targeted treatment of various types of melanoma." (PMID 33233603, 2020).
melanoma (continued). "In contrast, the combination of PLX4720 and α-amanitin did not increase the apoptotic rate in the BRAF- and NRAS-wildtype melanoma cell line MeWo." (PMID 31123282, 2019). "In NFATc2+ EZH2+ melanoma cell lines pharmacological co-targeting of NFATc2 and EZH2 exerted strong anti-proliferative and pro-apoptotic activity, irrespective of BRAF or NRAS mutations and of BRAF inhibitor resistance." (PMID 30710146, 2019). "Conversely, our data revealed that NRAS-mutant melanoma cells were not particularly affected in oncogene-mediated signaling pathways, but rather showed a gene expression pattern in response to 1 exposure that was likely consistent with a phenotypic switch." (PMID 31635389, 2019). "Since there are hardly any publications on BRAF and NRAS wild type melanoma brain metastases cell lines, there are no results regarding the xenotransplantation behavior of this type of cells." (PMID 30858407, 2019). "SAMMSON is expressed in 90% of human melanomas and is essential to the viability of melanomas, irrespective of BRAF or NRAS mutational status." (PMID 31416288, 2019). "NGS revealed 118 (26%) of 446 melanomas with no mutation, 42% with BRAF mutations, 25% with NRAS mutations, 4.9% with KIT mutations, and 2.0, 2.7 and 2.7% with HRAS, KRAS and PIK3CA mutations, respectively." (PMID 31277584, 2019). "The zoledronic acid + GSK126 association exerted a strong anti-proliferative effect on BRAF-mutant, NRAS-mutant, and BRAF/NRAS wild-type melanoma cell lines, compared to treatment with single agents, and induced significant apoptosis on BRAF wild-type melanoma cell lines." (PMID 30710146, 2019). "We next applied our algorithm to melanoma cell culture single-cell data, which contain transcriptomes of tumor cells derived from three patients: two replicates of wild-type (WT), BRAF mutant-NRAS WT, and BRAF WT-NRAS mutant samples." (PMID 31266885, 2019). "Melanoma cells have been shown to be “addicted” to MITF and thus the NRAS*-mediated downregulation of MITF could cooperate with the upregulation of SPRY4 to suppress growth." (PMID 30651601, 2019). "The presence of NRAS and BRAF mutations in mucosal melanomas raises the question of their therapeutic potential for this particularly deadly form of melanoma, which has not yet fully benefited from genomics-era advances in precision oncology." (PMID 31398831, 2019). "We report data from the testing of our novel PDE8A – C-Raf disrupter/HOXD12 conjugate (from here on, named PPL-008) in MM415, a B-Raf inhibitor resistant malignant melanoma cell line (MM415; BRAF wt, KRAS wt, NRAS Q61L) and in an MM415 melanoma murine xenograft model." (PMID 30909892, 2019). "However, both NRAS Q61R and G12D mutant proteins activated ERK at variable levels, suggesting that the activation of MAPK pathway in melanoma is codon-independent." (PMID 31681616, 2019). "As in the NEMO study, comparing binimetinib with dacarbazine in NRAS mutant melanoma, this did not translate into an overall survival benefit." (PMID 30428063, 2019). "The patient populations in the current study and NEMO trial were different, as we included patients with neither NRAS- nor BRAF-mutant melanoma." (PMID 30428063, 2019). "Of note, mutations within this motif do not affect proper protein folding or proliferation of NRAS-mutant melanoma cells ectopically expressing these constructs." (PMID 29695835, 2018). "Nonetheless, univariate analysis clearly illustrated the prognostic value of ICAM-1 for MSS in NRAS/BRAF melanoma, where reduced expression is associated with worst survival, a finding that has not been widely reported in melanoma." (PMID 30116025, 2018). "In this study, we investigated the metabolic effects of SR4 and niclosamide, two small molecules that were recently identified as mitochondria uncouplers, against treatment naïve wild type, BRAFV600E and NRAS mutant, and BRAF inhibitor (vemurafenib)-resistant melanomas." (PMID 30651927, 2018).
melanoma (continued). "This analysis revealed that high BRD4 mRNA expression was associated with poor patient survival (P = 0.001) and disease‐free survival (P = 0.0008; Fig EV1) in NRAS‐mutant melanoma patients, but not in other genetic cohorts." (PMID 29650805, 2018). "The genomic landscape of melanoma, performed by The Cancer Genome Atlas (TCGA) on 333 melanoma samples delineated 4 genomic subtypes, i.e., triple wild-type (WT), BRAF mutant, NRAS, HRAS or KRAS mutant, and NF1 mutant, as well as three transcriptomic subclasses, i.e., immune, keratin and MIFT-low." (PMID 29743104, 2018). "In this study, we examined interferon-γ (IFNγ) responses in a large panel of immune checkpoint inhibitor-naïve melanoma cells with defined genetic drivers; BRAF-mutant (n = 11), NRAS-mutant (n = 10), BRAF/NRAS wild type (n = 10), and GNAQ/GNA11-mutant uveal melanomas (UVMs) (n = 8)." (PMID 29977240, 2018). "In the LMC, CD8+ T cell and NK cell scores were strongly predictive of melanoma-specific survival in double-WT tumors, but less so in BRAF-mutated and not at all in NRAS-mutated tumors; these differences were not matched by differences in cell scores." (PMID 29664013, 2018). "In the current study, we screened seven human melanoma cells lines representing distinct oncogenic drivers (two BRAF wild type, five BRAF600E and one NRAS mutant) for their basal metabolic phenotype and observed that all of them displayed OCR/ECAR ratio indicative of OXPHOS activity." (PMID 30651927, 2018). "Current therapies are not very efficient to treat NRAS‐mutant melanoma owing to its aggressive nature and the complex changes in molecular signaling." (PMID 29661909, 2018). "In addition, RAC1 is also a crucial kinase in the NRAS and PI3K pathway, both of which are key melanoma oncogenic pathways." (PMID 29342889, 2018). "Our studies have uncovered BRD4 as a key vulnerability in NRAS‐mutant melanoma and establish that co‐targeting BET and MEK may be an effective strategy that could be rapidly translated for the treatment of melanoma refractory to current therapies." (PMID 29650805, 2018). "To rule out this possibility, we treated NRAS-mutant melanoma cells with a cdk4/6 inhibitor to induce cell cycle arrest and assessed TERT levels." (PMID 29695835, 2018). "While BET or MEK inhibitors predominantly induced cytostatic effects as single agents, the combination of both compounds triggered significant apoptosis selectively in NRAS‐mutant melanoma cells without affecting non‐transformed cells (Fig EV3D)." (PMID 29650805, 2018). "Single-cell RNA-seq data of three melanoma short-term cultures of BRAF/NRAS double wild type (wt/wt), BRAF-mutant/NRAS-wild type (BRAF-mut/NRAS-wt) and BRAF wild type/NRAS-mutant (BRAF-wt/NRAS-mut) cells were analyzed regarding PT dynamics to assess mechanisms of tumor progression." (PMID 29614062, 2018). "A signature characterizing the pigmentation subtype of melanomas shows a bipolar expression pattern with high activity in the wt/wt cell culture and low activity in the BRAF-wt/NRAS-mut cell culture, and a fluctuating expression in BRAF-mut/NRAS-wt cells." (PMID 29614062, 2018). "To determine whether vemurafenib and dabrafenib had differential effects upon the growth of BRAF‐ and NRAS‐mutant melanoma cells, we treated 1205Lu (BRAF mutant) and WM1366 cells (NRAS mutant) chronically (>14 days) with each drug and performed cell counts." (PMID 29112787, 2018). "HSP90 inhibition by 17-AAG inhibits ERK signaling and cell growth by destabilizing CRAF but not BRAFWT in the majority of NRAS mutant melanoma cells." (PMID 29481571, 2018). "Targeted cancer therapies have shown some progress in treating BRAF‐mutant melanoma, but not against NRAS‐mutant and treatment‐resistant melanoma." (PMID 29661909, 2018). "Together, these data suggest that the combination treatment is more potent than single drugs in killing the MICs in most of melanoma tested, and the mutation status of BRAF or NRAS did not influence the effects." (PMID 30185782, 2018).